LEP (leptin)
Diseases named in the same sentence as LEP in open-access papers (continued):
Sharing a sentence is not in itself a finding about the gene and the disease.
Obesity (continued). "As of now, the discovery of leptin has taught us more about a powerful peripheral signal that communicates with central neural energy balance circuits to signal the switch between starvation and the fed state than about mechanisms to control body weight or treat obesity." (PMID 30357355, 2019). "Furthermore, it is though that maternal glucose regulates cord blood leptin levels and this could explain why newborns exposed to GDM have an increased risk of obesity." (PMID 29160594, 2018). "In addition, the mechanisms of obesity promoting gonadal axis initiation include leptin." (PMID 30387539, 2018). "Moreover, it was suggested that the increased serum leptin levels, observed in obesity, could control immunity by negatively affecting Treg cell proliferative capacity and function." (PMID 29758052, 2018). "However, the central satiety effects of leptin are abrogated in obesity." (PMID 29675134, 2018). "In sum, increasing the dietary amount of lard-based fat from 10 to 45% or 60% of the total energy intake leads to obesity accompanied by increased fasting blood glucose and insulin (pointing toward reduced insulin sensitivity), reduced glucose tolerance and increased plasma leptin." (PMID 30670942, 2018). "During development, fatty acids and sugars, as well as satiety hormones, like insulin and leptin, and inflammatory factors related to obesity-induced low grade inflammation, could play a role in the impairment of neuroendocrine system and brain neuronal circuits regulating behavior in offspring." (PMID 29563885, 2018). "Therefore, targeting PTP1B and SOCS3 may prove valuable to overcome central leptin resistance in obesity, aging, and AD." (PMID 30692905, 2018). "The purpose of this study was to evaluate the effect of weight loss induced by surgery for obesity and weight-related diseases on pro-inflammatory cytokine (TNF-α) and anti-inflammatory adipokine (adiponectin) levels, and on an adipose-derived hormone (leptin) in severely obese subjects." (PMID 29497960, 2018). "It has been suggested that IL-15 and aberrant leptin secretion with obesity might instigate an adipose-specific NK-cell expansion and activation in response to high-fat diet overfeeding, stimulating NK-cell IFN-γ, TNF-α, and MCP-1 production, negatively impacting whole-body insulin sensitivity." (PMID 29479350, 2018). "Besides the relevance of fasting levels of leptin and ghrelin individually, the L/G ratio may be more sensitive to predict alterations related with metabolic syndrome components, like obesity and insulin resistance." (PMID 29618984, 2018). "Previous studies analyzing crosstalk between metabolism and reproductive function determined that GnRH neurons may integrate obesity-induced changes in glucose directly, but changes in insulin and leptin are most likely relayed indirectly via neuronal afferents that synapse to GnRH neurons." (PMID 30254630, 2018). "Interestingly, leptin and adiponectin expression in adipose tissue at weaning and at the time before the onset of obesity could be defined as early biomarkers of metabolic disturbance, predisposing towards adult obesity under the appropriate environment." (PMID 29329236, 2018). "Consequently, we hypothesized that high concentrations of serum leptin during obesity might modulate D2 receptor‐mediated effects on VTA dopaminergic neurons." (PMID 29611323, 2018). "Treatment for leptin-increased obesity may be a treatment for OA." (PMID 29620639, 2018). "Therefore, a deficiency of leptin signaling either via lacking leptin or leptin resistance encourages to overeating and ultimately causes some heritable and acquired types of obesity." (PMID 30400600, 2018). "However, several studies performed on animal models and humans led to the conclusion that diet-induced obesity may result in leptin resistance." (PMID 30131766, 2018).
Obesity (continued). "Further, as leptin resistance is often reported in obesity and T2DM, enervate the regeneration of skeletal muscle in the ob/ob and db/db mouse models of obesity, also suggests that leptin deficiency or resistance could contribute to poor muscle regeneration and satellite cell function." (PMID 30258366, 2018). "Here, we aimed to determine whether leptin-reactive immunoglobulins (Ig) are present in obese and type 2 diabetes (T2D) patients and whether their plasma levels and affinity kinetics may correlate with obesity and diabetes markers." (PMID 29795184, 2018). "In addition, leptin knock-out mice exhibited hyperphagia and obesity while leptin administration could reverse theses effects." (PMID 29723298, 2018). "However, in obesity, leptin resistance is thought to impair leptin signaling." (PMID 29777232, 2018). "These associations remained significant after adjustment for obesity, suggesting that leptin SNPs may influence CRC risk independent of obesity." (PMID 30379922, 2018). "Circulating leptin is strongly associated with both subcutaneous and visceral fat, and different studies demonstrate that obesity might induce a state of leptin resistance, when, despite high plasma levels of leptin, the biological activity of this hormone is very low." (PMID 30388763, 2018). "We hypothesize that HFD-induced leptin secretion (with or without Lobe treatment) might be both a consequence and a cause of obesity." (PMID 29979770, 2018). "Additionally, the adiponectin: leptin ratio has been shown to correlate with variations in systolic BP, insulin sensitivity, total cholesterol and low-density lipoprotein in MetS patients with obesity." (PMID 30114249, 2018). "Indeed, an excitatory-to-inhibitory switch of synapses on orexin somata has been reported in obese mice, both in the genetic model of obesity represented by leptin-deficient ob/ob mice and in mice subjected to high-fat diet (HFD), a model of diet-induced obesity." (PMID 30319410, 2018). "In addition to leptin, our data also indicate that obesity exerts its effect on PAI-1." (PMID 29636702, 2018). "Moreover, gluten peptides may also contribute to leptin- and insulin resistance, regarding obesity and T2D." (PMID 30428550, 2018). "Moreover, higher plasma leptin levels are associated with CKD, and the authors of these studies sustain that leptin may explain part of the reported association between obesity and kidney disease." (PMID 30271792, 2018). "Furthermore, serum and synovial fluid may be involved in OA progression through the regulation of pro-inflammatory markers such as IL-1β, IL-6, IP-10, and leptin in obesity conditions." (PMID 29843440, 2018). "Therefore, targeting the leptin-Notch axis could be a novel way to improve 5-FU therapy for PC patients, especially in obesity context." (PMID 29719602, 2018). "Therefore, low levels of leptin or its biological inactivity resulting from mutations in LEP may disturb metabolic balance, leading to severe obesity and related metabolic disorders." (PMID 29217499, 2018). "Therefore, the aim of the present study was to examine whether RSV exerts part of its anti-obesity effect by modulating leptin sensitivity in the liver, skeletal muscle and adipose tissue." (PMID 30441779, 2018). "It was followed by identification of mutations in downstream effectors of leptin laying down the basis of monogenic obesity but the recent explosion of obesity could not be explained by these low frequency mutations." (PMID 29752338, 2018). "In addition, it may be involved in OA progression in serum and synovial fluid by the regulation of pro-inflammatory markers such as IL-1β, IL-6, IP-10, and leptin in the obesity condition." (PMID 29843440, 2018). "Leptin stimulates the release of IL-1β in the hypothalamus while a HFD does not appear to upregulate IL-1β in this brain area but IL-1β does increase in the periphery in obesity indicating a more complex relationship between HFD, IL-1β and serpinA3N upregulation." (PMID 30519364, 2018).
Obesity (continued). "Obesity is partially characterized by a state of long-term, highly elevated leptin exposure, and NK cells from obese animals were significantly resistant to leptin stimulation, which could explain the functional desensitization of NK cells after long-term exposure." (PMID 29910742, 2018). "The influence zinc has on adipocytes through the expression of leptin by promoting free fatty acid release and glucose uptake may be controlled through the expression of a number of zinc transporters in the adipocyte, which may be altered in obesity." (PMID 28165362, 2017). "In this context, the identification of ARC neuromediators other than those released by the POMC/CART and NPY/AgRP/GABA neurons that could relay the catabolic message of leptin via the melanocortin system, appeared justified in our understanding of the pathophysiology of obesity." (PMID 28690493, 2017). "In obesity, however, leptin fails to correct hyperglycemia, such that it is conceived that metabolic dysregulation and obesity may cause “leptin resistance”." (PMID 28758929, 2017). "As a consequence of obesity, an immune regulator as important as IKKβ/NF-κB is involved not only in meta-inflammation of peripheral tissues, but is also activated in the CNS, participating in hypothalamic inflammation and aggravating IR and Leptin resistance development." (PMID 28590409, 2017). "Moreover, both MeS and obesity are characterized by the activation of several inflammatory pathways, including cytokines as Interleukin-6, Tumor Necrosis Factor-alpha, Interleukin-1 and adipokines as leptin, adiponectin and resistin." (PMID 29112985, 2017). "Interestingly, leptin resistance in the ARC does not cause obesity, but it contributes to its persistence, as it develops secondarily after adiposity and body mass increase." (PMID 28303116, 2017). "We provide an extensive overview of current structural insights on the leptin–ObR interface and ObR activation, coupling to signaling pathways and their negative regulation, and leptin functioning under normal and pathophysiological conditions (obesity, autoimmunity, cancer... )." (PMID 28270795, 2017). "Consequently, suppression of leptin expression is an alternative against obesity." (PMID 28953247, 2017). "Therefore, we premise that increasing the number of individuals included to our study with children and adolescents with only a lighter obesity phenotype would not increase the probability of identifying a causal leptin gene mutation." (PMID 28542631, 2017). "The results are concurrent with the observations of other authors who stated that the plasma leptin concentration in women is two or three times higher than the concentration in the plasma of men with the same BMI as in women, both in the case of healthy individuals, as well as those with obesity." (PMID 28758947, 2017). "ADIPO and LEP are the two most abundant adipokines and as such are among the most intensively examined and have each been shown to affect the growth status of breast cancer cells, making them prime candidates responsible for the molecular link between obesity and breast cancer." (PMID 28873415, 2017). "Clearly, future studies will need to be performed to determine the exact role of the altered leptin surge per se we observed in response to moderate gestational hypoxia vs potential direct effects of gestational hypoxia on the programming of appetite dysregulation and obesity." (PMID 28957383, 2017). "While administration of exogenous leptin in WT mice significantly decreased food intake, fat mass, and body weight, in BBS-null mice the effects of leptin were abrogated, suggesting that leptin resistance could contribute to obesity development in BBS-null mice." (PMID 28913352, 2017). "Hence, lunasin decreased IL-1β secretion after leptin activation alone, indicating that this suppression might reduce obesity-induced inflammation and metabolic complications." (PMID 28182687, 2017).
Obesity (continued). "Among the six leptin-associated loci, three genes (MC4R, BDNF, and PCSK1) are known to be involved in the hypothalamic leptin–melanocortin pathway, thus it is not surprising that those three loci are found to be associated with obesity-related traits and leptin levels in our pediatric setting." (PMID 29212175, 2017). "However, using this approach, we were not able to identify any leptin gene mutation carriers among three probands with an early-onset severe obesity and the lowest bioactive leptin proportion (<90%)." (PMID 28542631, 2017). "In addition, we evaluate leptin as a risk factor for CVD independent of obesity while accounting for other obesity effects." (PMID 28278178, 2017). "The leptin levels were lower in patients with fibromyalgia and overweight/obesity when compared with control participants with overweight/obesity, which may indicate that the occurrence of fibromyalgia in overweight patients leads to decreased production of leptin." (PMID 28226002, 2017). "The findings of the present study are expected to lead to an improved understanding of the role of adiponectin and leptin in the etiology, pathogenesis, and prevention of prediabetics and diabetics if they can be replicated in other populations with low prevalence of overweight and obesity." (PMID 28786989, 2017). "Moreover, we found that the induction of PTPRJ may contribute to leptin resistance induced by obesity." (PMID 28912580, 2017). "Leptin is not only a multifunctional metabolic regulator altering food intake, energy expenditure and neuroendocrine function, but also has been reported to be an important mediator of obesity related pro-inflammatory state that contributes to metabolic disorders." (PMID 29020116, 2017). "This may reflect habitually high leptin levels in association with obesity, and non-specificity as a GDM marker." (PMID 28766127, 2017). "Moreover, leptin, the hormone produced by adipose tissue, is excessively secreted in obesity." (PMID 29070064, 2017). "Indeed, leptin and adiponectin levels have been found to be respectively positively and negatively correlated with obesity, diabetes mellitus, hypertension and metabolic syndrome.Leptin and adiponectin also have opposite’s effects on inflammatory markers and thus subclinical inflammation." (PMID 28878827, 2017). "We also note that our estimation does not account for compound heterozygous LEP mutations that may cause severe obesity." (PMID 29101506, 2017). "Further, there is strong evidence that production of leptin, a regulatory hormone mainly produced by adipocytes, can be altered by the maternal nutritional environment and is involved in prenatal or early postnatal programming of increased offspring appetite and obesity." (PMID 28771488, 2017). "Both CRP and leptin could play important role in the process of obesity." (PMID 28115972, 2017). "Higher gene expression levels of LEP, Pomc and Slc2a4 genes and lower levels of the Npy gene in breastfed individuals is in agreement with other epidemiological evidence that breastfeeding might protect against obesity and diabetes." (PMID 28257446, 2017). "Nevertheless, the phenotype of patients with deficiency or impaired bioactivity of leptin may not be easy to differentiate from common severe obesity and the condition could be underdiagnosed." (PMID 28542631, 2017). "Most of these abnormalities are linked with starvation, not with obesity; the lack of leptin signaling to inform the brain that adequate fat stores are present, elicits physiological responses that reduce energy expenditure and stimulate appetite, similar to when the organism is starving." (PMID 28303116, 2017). "As plasma and adipose tissue concentrations of proinflammatory cytokines, like IFN-γ and TNF-α, are elevated in obesity, the leptin-mediated decrease of IFN-γ secretion by NK cells may be a local effect occurring in regions of NK cell defense against tumor cells." (PMID 28357137, 2017).
Obesity (continued). "Our present data show that maternal exposure to CAP significantly decreased central leptin signaling, as reflected in elevated Npy mRNA expression, and plasma leptin level, suggesting that the increased food intake and obesity in male offspring may be mediated by a defect in leptin production." (PMID 28645299, 2017). "Whereas leptin has inhibitory effects on β-cell function and expansion under normal metabolic conditions, the high plasma leptin levels accompanying increased adiposity could play a role in β-cell adaptation in the setting of high fat diet-induced obesity in mice." (PMID 28168202, 2017). "In the acute phase, the expected association between BMI and leptin was not seen, and the difference in circulating levels between men and women was attenuated, indicating that leptin is not only a simple measure of obesity but also a complex hormone with acute-phase properties." (PMID 28919840, 2017). "Moreover, we observed an increase in WISP1 gene expression in adipose tissue from both diet-induced and leptin-deficient ob/ob obese mice, suggesting that WISP1 could be involved in the pathophysiological onset of obesity." (PMID 28496206, 2017). "While it is unclear whether the incidence of liver cancer is increased in leptin-deficient mice, there is no doubt that the risk for primary liver cancer is increased in humans with obesity-related liver disease, even in the absence of cirrhosis." (PMID 28427343, 2017). "Elucidating the molecular physiology of the leptin sensing neuron populations in each of these brain regions is essential to understanding the mechanisms by which obesity disrupts (and subsequent weight loss succeeds or fails to restore) leptin signaling in isolated brain nuclei." (PMID 28107353, 2017). "The influential role of leptin in the regulation of energy homeostasis led us to ask whether deletion of the Bbs1 gene specifically in the LRb-expressing cells will recapitulate the obesity phenotype of BBS." (PMID 26926121, 2016). "Although genetically engineered mice models such as ob/ob (mice unable to produce leptin) or db/db (mice unable to respond to leptin) are available for obesity research, they lack convincing evidence for whether leptin-related mutation can represent typical obesity in humans." (PMID 28008317, 2016). "The discovery of leptin led to the expectation that leptin therapy may be beneficial for obesity." (PMID 27375555, 2016). "In addition, obesity is also related to elevations in circulating leptin concentrations, which could alter the expression of these amino acid NTs in the jejunum." (PMID 27801863, 2016). "Having observed significant insulin and leptin resistance in young SF-1 KO mice, we speculated that hormonal dysregulation might already have occurred at a younger age before the development of obesity in aged KO mice." (PMID 27598259, 2016). "Although exchanging sugar for fat alone may not increase rates of obesity as shown in a recent systematic review, eating food high in sugar may promote consumption of excess calories by inducing leptin resistance and increasing the risk of obesity." (PMID 26807511, 2016). "More specifically, pediatric obesity is associated with higher TSH and lower FT4 concentrations and with a greater prevalence of abnormally high TSH and leptin concentrations that might in part explain obesity’s effects on thyroid status, perhaps through leptin’s influences on TSH secretion." (PMID 27610076, 2016). "Leptin could play an important role in the rise of obesity-related cancer incidence." (PMID 27472371, 2016). "The study in mice transplanting human fecal microbiota from twins discordant for obesity revealed that increasing intestinal SCFAs by the lean co-twin’s microbiota influenced host energy balance, inhibited the accumulation of fat in adipose tissue and promoted leptin level." (PMID 27255518, 2016).